PRC1 (protein regulator of cytokinesis 1)
Description:
Key regulator of cytokinesis that cross-links antiparrallel microtubules at an average distance of 35 nM. Essential for controlling the spatiotemporal formation of the midzone and successful cytokinesis. Required for KIF14 localization to the central spindle and midbody. Required to recruit PLK1 to the spindle. Stimulates PLK1 phosphorylation of RACGAP1 to allow recruitment of ECT2 to the central spindle. Acts as an oncogene for promoting bladder cancer cells proliferation, apoptosis inhibition and carcinogenic progression.
Synonyms: ASE1; MAP65
Tractability: Small molecule: a structure with a bound ligand is known. Antibody: its Gene Ontology location is reachable by antibodies, with high confidence. PROTAC: ubiquitination databases record sites on it.
Gene: Protein-coding gene on chromosome 15 (90,966,038 to 90,995,629, reverse strand). Ensembl gene ENSG00000198901.
Subcellular location: Nucleus; Cytoplasm; Cytoplasm, cytoskeleton, spindle pole; Midbody; Chromosome
Subcellular location (Human Protein Atlas): Cytokinetic bridge; Microtubules; Midbody; Nucleoplasm; Plasma membrane
Pathways (Reactome):
Signal Transduction: RHO GTPases activate CIT
Gene Ontology:
Molecular function: kinesin binding; protein binding; protein kinase binding; microtubule binding
Biological process: positive regulation of cell population proliferation; regulation of cytokinesis; mitotic spindle elongation; mitotic spindle midzone assembly; microtubule cytoskeleton organization
Cellular component: chromosome; contractile ring; microtubule cytoskeleton; midbody; nucleoplasm; nucleus; spindle; cytosol; mitotic spindle midzone; spindle microtubule; cytoplasm; spindle pole
Genetic constraint (gnomAD): Loss-of-function variants: 51 observed, 91.32 expected, observed/expected ratio (o/e) 0.56, 90% interval 0.44 to 0.7. The upper end of that interval is the gene's LOEUF score, 0.7, which puts it in group 2 of 6, group 1 being the genes least tolerant of losing a copy. Missense variants: 715 observed, 773.42 expected, observed/expected ratio (o/e) 0.92, 90% interval 0.87 to 0.98. Synonymous variants: 274 observed, 275.74 expected, observed/expected ratio (o/e) 0.99, 90% interval 0.9 to 1.1.
Homologues: Orthologues: chimpanzee PRC1 (99% identical), macaque PRC1 (98% identical), dog PRC1 (93% identical), pig PRC1 (90% identical), guinea pig PRC1 (88% identical), mouse Prc1 (84% identical), rat Prc1 (83% identical), rabbit PRC1 (82% identical), tropical clawed frog prc1 (63% identical), zebrafish prc1b (58% identical), zebrafish prc1a (49% identical).
Diseases named in the same sentence as PRC1 in open-access papers:
PRC1 is named in the same sentence as 141 diseases in open-access papers, as found by Europe PMC text mining. Sharing a sentence is not in itself a finding about the gene and the disease. The quoted sentences say what the papers report.
breast cancer (48 papers, 2010 to 2025). A primary or metastatic malignant neoplasm involving the breast. "In breast cancer cells, phosphorylation of PRC1 by the CDK16/CCNY complex has been linked to accelerated cell cycle progression and tumor growth." (PMID 40665337, 2025). "Knockdown of either PRC1 or KIF2C inhibited proliferation of multiple breast cancer cell lines, which was associated with morphological changes especially during mitosis, in these cancer cells." (PMID 38344808, 2024). "AKT phosphorylates PCGF2 to disrupt the interaction between PCGF2 and other PRC1 members that cause tumorigenesis in breast cancer." (PMID 39337298, 2024). "The UBCH5 isoforms ubiquitinate histone H2A in concert with PRC1 in vitro, and TRIM37, an E3 ligase that associates with PRC2, ubiquitinates H2A in human breast cancer cell lines where RING1B of PRC1 is down-regulated." (PMID 30282802, 2018). "Here, we show that RNF2, encoding RING1B, and canonical PRC1 (cPRC1) genes are overexpressed in breast cancer." (PMID 30139998, 2018). "While PRC1-encoding genes are not typically mutated in cancer, we found that several canonical PRC1 genes are amplified and dysregulated in many hormone-related cancers, including breast cancer." (PMID 30139998, 2018). "Since PRC1 exhibits a variable composition of proteins we also investigated Bmi1, that has been found overexpressed in breast cancer, where it is associated with a good prognosis." (PMID 24742605, 2014). "However, the analysis revealed 3 somatic mutated genes: CDC42BPA, EXT1, and PRC1 significantly associated with both types of breast cancer." (PMID 32724790, 2020). "To determine whether these findings are of clinical significance, we asked whether expression of KIF23 and PRC1 is associated with prognosis of breast cancer by examining previously published microarray data sets." (PMID 28061449, 2017). "According to previous findings, PRC1 is regarded as an oncoprotein in diverse human cancers such as oral cancer, breast cancer, and hepatocellular carcinoma." (PMID 40847353, 2025). "In terms of cellular composition, the enrichment of “receptor complexes, PcG protein complexes, and PRC1 complexes” suggests that these structures are important in the biological behavior of breast cancer cells." (PMID 41319483, 2025). "Existing literature has shown that CDK16 modulates tyrosine phosphorylation of PRC1 at the T481 site in breast cancer cells." (PMID 40665337, 2025). "PRC1 also regulates the tumorigenesis of other types of cancer, including breast cancer, uveal melanoma, ovarian cancer, and childhood cancers, such as Ewing sarcoma (EwS)." (PMID 37098483, 2023). "Although the exact PRC1-mediated mechanism that promotes gene transcription in breast cancer cells is not fully understood, similarly to PRC2, RNA is required for PRC1 stabilization at chromatin upon estrogen induction." (PMID 36105358, 2022). "RNF2 is the core subunit of PRC1, which is a negative regulator of anti-tumor immunity in various human cancers, including breast cancer." (PMID 36553670, 2022). "Intriguingly, TCGA analysis revealed that PRC1 was highly expressed in breast cancer, especially in TNBC, and its high expression was significantly correlated with poor prognosis." (PMID 35449080, 2022). "PRC1 was significantly overexpressed in breast cancer and lung adenocarcinoma, despite the possible molecular mechanisms have not been fully elucidated." (PMID 34917133, 2021). "The abnormal regulation of PRC1 contributed to cancer progress, such as prostate cancer and breast cancer." (PMID 34384030, 2021). "Consistently, a previous report revealed PRC1 was accumulated in the breast cancer, and PRC1 promoter exhibited cancer-specific activity." (PMID 33292244, 2020).
breast cancer (continued). "An abnormally high expression of PRC1 has been observed in breast cancer, bladder cancer, hepatocellular carcinoma, and pancreatic cancer, which suggests a promotive role of PRC1 in tumorigenesis." (PMID 30881920, 2019). "As the only upregulated hub gene, PRC1 is involved in the process of cytokinesis and is upregulated in breast cancer, hepatocellular carcinoma, and lung cancer." (PMID 31333911, 2019). "Since the breast cancer data sets contain the largest number of patient samples and thus provide the most robust data, we further analyzed PRC1 genes in these patient samples." (PMID 30139998, 2018). "Here, the authors investigate canonical PRC1’s regulation of transcriptional programs in breast cancer where, in addition to its repressive function, it is also recruited to oncogenic active enhancers to regulate enhancer activity and chromatin accessibility." (PMID 30139998, 2018). "We found that KIF23, KIF20A, KIF4A, KIFC1 and PRC1 were expressed at high levels in all investigated breast cancer cell lines." (PMID 28061449, 2017). "We next examined expression of KIF23 and PRC1 in breast cancer gene expression datasets grouped according to HU and PAM50 subtypes." (PMID 28061449, 2017). "PRC1 is overexpressed in a variety of cancers, including breast cancer 12, bladder cancer 13, hepatocellular carcinoma 14, 15 and pancreatic cancer." (PMID 28190297, 2017). "It has already been documented that PRC1 is overexpressed in different cancers, such as breast cancer, bladder cancer, hepatocellular carcinoma, and pancreatic cancer." (PMID 28646916, 2017). "In ER+ breast cancer, the steroid hormone estrogen recruits PRC1 to ERα target genes." (PMID 36105358, 2022). "PRC1 is recognized as an oncoprotein in various cancer types, including breast cancer." (PMID 35449080, 2022). "Besides, evidence suggests that PRC1 is involved in breast tumorigenesis, and it is a promising target for clinical treatment of breast cancer." (PMID 33292244, 2020). "Moreover, application of this integrated strategy revealed insights into mitochondrial function following PGC1a and PRC1 inhibition in pancreatic cancer and demonstrated how the Rho-GTPases impact mitochondrial dynamics in breast cancer." (PMID 32472013, 2020). "Here, we show that PRC1 genes are genetically amplified in breast cancer." (PMID 30139998, 2018). "Whether hormones contribute to chromosome instability and genomic rearrangements of genomic sites of PRC1 genes in breast cancer remain to be addressed." (PMID 30139998, 2018). "KIF23 and PRC1 could be used as prognostic biomarker and could be potential therapeutic targets for the treatment of breast cancer." (PMID 28061449, 2017). "Inhibition of KIF23 and PRC1 had strong antiproliferative effects in breast cancer cells." (PMID 28061449, 2017). "A study indicated that the higher expression level of the PRC1 gene could be a predictor of the poor prognosis for breast cancer patients." (PMID 27705907, 2016). "Indeed, the absence of scm in Drosophila induces an increase in proliferation similar to that associated with defects in PRC1 components, and human SCML2 and other MBT-containing genes are focally deleted in medulloblastomas and breast cancer." (PMID 24358021, 2013). "DTL, ECT2, MTDH, PRC1 and RFC4 have all been previously implicated in breast cancer; SCUBE2 and STK32B deletions have been found to be related to mental deficits in humans; and ZNF533 has been found to be associated with the Hedgehog signaling pathway in Zebrafish." (PMID 20584321, 2010). "Finally, based on the results of five validation data sets and the support of existing literature, we hypothesized that IRS1 and PRC1 may play an important role in breast cancer resistance." (PMID 35387129, 2022).
breast cancer (continued). "have shown that promoters of the protein regulator of cytokinesis 1 (PRC1) and ribonuclease reductase 2 (RRM2) genes can be used in targeting breast cancer cells because these promoters exhibit strong gene expression similar to that driven by the CMV promoter." (PMID 38149057, 2023). "Up to now, the role of Polycomb in breast cancer has been mainly addressed to investigate the expression or the function of two Polycomb proteins, EZH2 and BMI1 (PRC2 and PRC1 complexes, respectively)." (PMID 24742605, 2014). "We developed a prognostic tool for early breast cancer based on the analysis of the relative expression level of FGF18, BCL2, PRC1, MMP9 and SERF1A in combination." (PMID 23648477, 2013). "Protein regulator of cytokinesis 1 (PRC1) is essential for organization of central spindle and midzone formation, whose interaction with KIF2C has been shown to be involved in breast cancer tumorigenesis." (PMID 21501490, 2011). "Moreover, two in vitro studies showed that protein regulator of cytokinesis 1 (PRC1) and KIF2C formed a functional complex and that both were upregulated in several breast cancer cell lines." (PMID 38344808, 2024). "Through functional enrichment analysis, immune microenvironment analysis, and other computational analysis methods, we identified PRC1, GGTLC1, and IRS1 as genes that may mediate breast cancer chemoresistance through the immune pathway." (PMID 35387129, 2022). "We discovered three genes: PRC1, GGTLC1, and IRS1 that may mediate breast cancer chemotherapy resistance through immune pathways and found that immune regulation disorders may be some of the key factors in the survival of breast cancer patients." (PMID 35387129, 2022). "Through the random walk method, we finally identified that GGTLC1, PRC1, and IRS1 may have produced breast cancer drug-resistant phenotypes through immune-mediated pathways." (PMID 35387129, 2022). "However, CBX7 content in breast cancer is often very low, indicating that CBX7 plays its other tumor suppressor role independently of PRC1." (PMID 34659360, 2021). "We demonstrate that six mitotic kinesins and two microtubule-associated non-motor proteins (MAPs) CEP55 and PRC1 are direct transcriptional targets of MuvB, B-MYB and FOXM1 in breast cancer cells." (PMID 28061449, 2017). "Interestingly, the mechanism of increasing PTEN transcription may be the same as the enhanced DKK-1 expression in breast cancer, where CBX7 recruits p300 independently of PRC1 to the promoter region to participate in epigenetic changes." (PMID 34659360, 2021). "How noncanonical PRC1 participates in E-cadherin transcription in breast cancer is unknown." (PMID 33608512, 2021).
hepatocellular carcinoma (26 papers, 2013 to 2025). A malignant tumor that arises from hepatocytes. "In hepatocellular carcinoma, likewise, high PRC1 expression has been linked to increased TAM infiltration and poor prognosis of patients." (PMID 37647439, 2023). "Previous bioinformatics analyses have revealed that PRC1 was associated with immune invasion of hepatocellular carcinoma." (PMID 35387129, 2022). "The previous studies have implicated that PRC1 as an oncogenic factor in tumorigenesis of breast, bladder cancer, hepatocellular carcinoma and gastric carcinoma." (PMID 28646916, 2017). "Moreover, PRC1 was recently shown to promote early recurrence of hepatocellular carcinoma in association with Wnt/β-catenin signaling pathway." (PMID 31867100, 2019). "In hepatocellular carcinoma (HCC), ZFP36 functions as a tumor suppressor by destabilizing oncogenic mRNAs such as PRC1, CCND1, and CDK6, which are implicated in cell cycle progression and tumor growth." (PMID 40361912, 2025). "It has already been reported that PRC1 is overexpressed in different cancers, such as hepatocellular carcinoma and pancreatic cancer." (PMID 33937050, 2021). "Kinesis member PRC1 was upregulated in hepatocellular carcinoma compared with normal liver or paracancerous tissues and was positively associated with vascular invasion and high grade of cancer." (PMID 33995648, 2021). "Recently, PRC1 was shown to promote malignant properties of hepatocellular carcinoma via activation of Wnt/β-catenin signaling pathway." (PMID 31867100, 2019). "Herein we demonstrate overexpression of protein regulator of cytokinesis 1 (PRC1), a microtubule-associated regulator of mitosis, in human hepatocellular carcinoma (HCC)." (PMID 29748662, 2018). "Recently, a link between PRC1 and Wnt/ßcatenin signaling in hepatocellular carcinoma (HCC) has been observed." (PMID 29435157, 2018). "Recently, it has been reported that expression of PRC1 is induced by Wnt in hepatocellular carcinoma (HCC) cell lines." (PMID 29435157, 2018). "The activation of Wnt target genes by PRC1 promotes proliferation, stemness and metastasis of hepatocellular carcinoma." (PMID 29435157, 2018). "For example, activation of the ß-catenin dependent transcription by PRC1 promoting proliferation, stemness and metastasis of hepatocellular carcinoma has recently been reported." (PMID 28061449, 2017). "In addition, PRC1 has been demonstrated to regulate the Wnt/β-catenin signaling in hepatocellular carcinoma." (PMID 40847353, 2025). "Interestingly, Zfp36 exerts influence in the treatment of hepatocellular carcinoma by regulating PRC1, while it also plays an anti-tumor role through the knockdown of Zfp36 expression to affect inflammation, metabolism and cell proliferation." (PMID 35923893, 2022). "Recently, knockdown of PRC1 was shown to inhibit cell proliferation of hepatocellular carcinoma." (PMID 31867100, 2019). "In previous studies, the overexpression of PRC1 mediated the early recurrence of hepatocellular carcinoma through the Wnt/β-catenin signaling pathway and increased the resistance of HCC to paclitaxel." (PMID 35387129, 2022). "PRC1, a novel Wnt target, functions in a positive feedback loop that reinforces Wnt signaling to promote early Hepatocellular carcinoma (HCC) recurrence." (PMID 34642262, 2021). "Recent studies in hepatocellular carcinoma (HCC) showed that increased AKIP1 and PRC1 expression leads to activation of Wnt signaling, which promotes early HCC recurrence." (PMID 34446021, 2021). "It has also been reported that PRC1 controls the expression and function of wrrag such as FANCI, SPC25, KIF11, and KIF23 via Wnt signaling in hepatocellular carcinoma (HCC)." (PMID 40400636, 2025).
hepatocellular carcinoma (continued). "It has been shown to reduce hepatocellular carcinoma cell proliferation by targeting SOX9 and to suppress lung adenocarcinoma cell tumorigenesis in vivo by binding to PRC1." (PMID 39684278, 2024). "Knockdown of PRC1 inhibited the transcriptional activity of transcription factor (TCF), and reduced Wnt target expression of nuclear β-catenin levels in hepatocellular carcinoma." (PMID 28646916, 2017).